SLC7A2 (solute carrier family 7 member 2)
Diseases named in the same sentence as SLC7A2 in open-access papers (continued):
Sharing a sentence is not in itself a finding about the gene and the disease.
Stroke (1 paper, 2021). Sudden impairment of blood flow to a part of the brain due to occlusion or rupture of an artery to the brain. "Given the involvement of macrophages in modulating infarction after stroke and the role of Slc7a2 in L-arginine transport to maintain macrophage activation, Slc7a2 may indeed have a neuroprotective function following an ischemic event in the brain, warranting further investigation." (PMID 34408625, 2021).
thyroiditis (1 paper, 2018). Inflammation of the thyroid gland. "Thyroiditis was significantly correlated with SLC7A2, SLC7A3, SLC7A7, and SLC7A9." (PMID 30558624, 2018).
triple-negative breast carcinoma (1 paper, 2024). An invasive breast carcinoma which is negative for expression of estrogen receptor (ER), progesterone receptor (PR), and human epidermal growth factor receptor 2 (HER2). "In triple-negative breast cancer, solute carrier family 7 member 2 (SLC7A2) mediates lysine catabolism and promotes histone crotonylation by upregulating ACOX1." (PMID 39513918, 2024).
tumor (22 papers, 2013 to 2025). "Tumor from deficient SLC7A2 mice exhibited significantly increases levels of the multiple proinflammatory cytokines and chemokines, which is accompanied by pro-tumorigenic M2 macrophage activation." (PMID 34108444, 2021). "Collectively, these findings provided the important mechanism of SLC7A2-mediated tumor immune evasion through attracting MDSCs and put forth blockage of MDSCs recruitment as a prospective immunotherapy strategy for the treatment of SLC7A2 deficiency HCC metastasis." (PMID 34108444, 2021). "Because there were nearly 200 DEGs related to immune responses in cisplatin- and paclitaxel- resistant NSCLC cells, and tumor infiltrating lymphocytes are crucial for tumor patients’ survival, we tested if SLC7A2 expression could be associated with immune infiltration in NSCLC in the TIMER database." (PMID 36639771, 2023). "The results showed that the footpad tumor tissues of five pairs of mice were harvested in this experiment, and IHC confirmed that the expression of SLC7A2 in the OE‐SLC7A2 group was higher than that in the vector group." (PMID 39382373, 2024). "Serial sectioning and immunohistochemical staining for LYVE1 were performed to assess tumor‐associated lymphangiogenesis by measuring MLVD, and its relationship with SLC7A2 expression was examined." (PMID 39382373, 2024). "SLC7A2 likely exerts its anti‐tumor effects by regulating cell cycle‐related proteins or influencing specific signaling pathways." (PMID 39382373, 2024). "Overexpression of ACOX1 significantly antagonizes the depletion of SLC7A2 and inhibits tumor cell proliferation and growth." (PMID 39513918, 2024). "We found that CCL20 knockdown combined with SLC7A2 overexpression significantly lessened the tumor volume." (PMID 36969014, 2023). "We wanted to explore the SLC7A2 function in regulating tumor responses to tumor immunity, so we performed subcutaneous model with SLC7A2 knockdown Hepa1-6 cells in immune-competent C57BL/6 and immunodeficient mice." (PMID 34108444, 2021). "IHC staining for Ki67 in the tumor cells suggested that suppressed SLC7A2 in the proliferation of tumor cells has largely increased." (PMID 34108444, 2021). "Based on these findings, SLC7A2 served as a tumor suppressor gene that suppresses HCC cell growth and metastasis in vitro." (PMID 34108444, 2021). "Deficient SLC7A2 drove MDSC recruitment by upregulation of expression CXCL1 through PI3K/Akt/NF-kκB pathway, thus avoiding immune surveillance and promoting tumor progression." (PMID 34108444, 2021). "We have done more work to understand the mechanism of SLC7a2 regulating tumor growth and metastasis in vitro." (PMID 34108444, 2021). "In conclusion, G9a-mediated silencing of SLC7A2 exerts unexpected functions in cancer metastasis by fostering a tumor-supportive microenvironment through CXCL1 secretion and MDSCs recruitment." (PMID 34108444, 2021). "We further found that deficient SLC7A2 medicated the upregulation of CXCL1 through PI3K/Akt/NF-kκB pathway to recruit myeloid-derived suppressor cells (MDSCs), exerting tumor immunosuppressive effect." (PMID 34108444, 2021). "Furthermore, the research will focus on developing small molecule modulators that target SLC7A2 to enhance its capacity to inhibit tumor metastasis." (PMID 39382373, 2024). "SLC7A2 may act as a tumor suppressor to modulate drug sensitivity, immune infiltration and survival in NSCLC." (PMID 36639771, 2023). "Furthermore, CCL20 knockdown combined with SLC7A2 overexpression availably weakened the tumor growth in vivo." (PMID 36969014, 2023). "SLC7A2 may act as a tumor suppressor, it was found lower expression in NSCLC tissues and cell lines." (PMID 36639771, 2023). "ALKHB5, SLC7A2, and CGB3 showed a similar tendency to inhibit tumor development, suggesting that SLC7A2 and CGB3 may also play a suppressor role in GC; the internal mechanism of how ALKBH5 regulates these genes needs to be further explored." (PMID 36686788, 2022).
tumor (continued). "A subcutaneous mouse model was used in immunodeficient mice and the data indicated that tumor growth was not affected by SLC7A2 deficiency in immunodeficient mice." (PMID 34108444, 2021). "Interestingly, an immunocompetent subcutaneous HCC mouse model in C57BL/6 was served as tumorigenesis and the results showed that SLC7A2 overexpression significantly suppressed tumor growth." (PMID 34108444, 2021). "An increasing number of studies show that SLC7A2 is related to tumor progression and inflammation responses, but its importance and detailed molecular mechanisms remain unknown." (PMID 34108444, 2021). "IHC staining showed that knock-down SLC7A2 tumor cells were positively CD11b but negatively CD8." (PMID 34108444, 2021). "Furthermore, mice lacking SLC7A2 exhibit high levels of tumor‐promoting M2 macrophages and an increased risk of inflammation‐related colon tumorigenesis due to the mediation of various chemokines." (PMID 39382373, 2024). "Additionally, the overexpression of SLC7A2 may modify certain factors within the tumor microenvironment, thereby inhibiting tumor invasion and metastasis." (PMID 39382373, 2024). "First, although we found that lower SLC7A2 expression was associated with worse prognosis of NSCLC, and its deficiency aggravated chemoresistance, we did not determine whether and how SLC7A2 could modulate the influx transporter of multiple anti-tumor drugs." (PMID 36639771, 2023). "In addition, SLC7A2 is a transmembrane transporter, and it may help intracellular delivery of anti-tumor drugs." (PMID 36639771, 2023). "These suggest that SLC7A2 may act as a tumor suppressor during the development of malignant tumors." (PMID 36639771, 2023). "Furthermore, knockdown SLC7A2 promoted intrahepatic and lung metastasis and number of metastatic lung nodules, resulting in extended overall survival time in Hepa1-6-shSLC7A2 than its controls with intrahepatic tumor implantation experiment." (PMID 34108444, 2021). "In tumor cells, lysine uptake is facilitated through membrane receptors such as SLC7A1, SLC7A2, and SLC7A3, with SLC7A2 being the predominant transporter." (PMID 40399304, 2025). "Upregulation of SLC7A2 enhances ACOX1 expression and mediates CD8+ T cell histone Kcr to promote lysine release and inhibit tumor growth in TNBC patients." (PMID 39513918, 2024). "The downregulation of SLC7A2 upregulated CXCL1 through the PI3K/Akt/NF-κB pathway, recruiting bone marrow-derived suppressor cells and exerted a tumor immune inhibitory effect." (PMID 38287304, 2024). "In vivo experiments further confirmed that the upregulation of SLC7A2 can inhibit LNM, tumor growth, and the formation of tumor‐related lymphatics." (PMID 39382373, 2024). "After 30 days, we measured the tumor weight and observed that tumor weight was distinctly lowered by CCL20 knockdown combined with SLC7A2 overexpression." (PMID 36969014, 2023). "Subsequently, we extracted total RNA from different tumor cell lines (SMMC7721, Huh7, HepG2, and HCCLM3) and the normal liver cell lines (WLR68, and LO2) to measure the mRNA expression levels of CCL20, and SLC7A2." (PMID 36969014, 2023). "Given that SLC7A2 serves as a regulator MDSCs which contributes to immune responses and cytokines and chemokines, so we intended to figure out whether SLC7A2 affects MDSCs function resulting in tumor immunity and cytokines and chemokines to promote HCC progression." (PMID 34108444, 2021). "This cell line also mostly mimicked downregulated small molecule transporters seen in tumours, e.g. NPC1L1, SLC25A15/20, SLC2A2, SLC1A1 and SLC7A2." (PMID 30176945, 2018). "To understand the biological roles of SLC7A2, we generated SLC7A2-silenced A549-shRNA-SLC7A2 and H460-shRNA-SLC7A2 cells and found that SLC7A2 silencing promoted the proliferation of NSCLC cells, suggesting SLC7A2 may be a tumor suppressor in NSCLC." (PMID 36639771, 2023).
tumor (continued). "Analysis of SLC7A2 mRNA transcripts in different types of cancer and adjacent normal tissues in the TIMER database exhibited that the relative levels of SLC7A2 mRNA transcripts in LUAD and LUSC were significantly lower than that in adjacent non-tumor lung tissues." (PMID 36639771, 2023). "The results indicated that the levels of SLC7A2 transcripts were positively correlated to the levels of macrophage, neutrophil and dendritic cell infiltrates in LUSC and to the tumor purity, B cell, CD8+ T cell, CD4+ T cell, macrophage, neutrophil and dendritic cell infiltrates in LUAD." (PMID 36639771, 2023). "Activation of AMPK has up-regulated SLC7A2 expression and enhanced the sensitivity of NSCLC cells to anti-tumor drugs, which could be attributed to E2F1’s regulation." (PMID 36639771, 2023). "Similarly, significantly lower levels of SLC7A2 mRNA transcripts were detected in NSCLC A549 and H1975 cells, relative to that in lung non-tumor Beas2B and HBE cells." (PMID 36639771, 2023). "Furthermore, SLC7A2 played a role in suppressing tumors in HCC and enhanced tumor immune surveillance in the tumor microenvironment." (PMID 34108444, 2021). "Negative SLC7A2 expression was significantly increased tumor size and higher tumor-nodule-metastasis (TNM) stage." (PMID 34108444, 2021). "However, SLC7A2 function in regulating tumor responses to tumor immunity has not been explored." (PMID 34108444, 2021). "As ADMA generation has to occur in live cells (due to the requirement for active proteasomal or autophagosomal degradation and transport of ADMA via the ATP-dependent transporter, Slc7a2), ADMA in the medium was not due to apoptosis (induced by activated splenic T cells) or rupture of tumor cells." (PMID 36376929, 2022).
cancer (14 papers, 2016 to 2025). A tumor composed of atypical neoplastic, often pleomorphic cells that invade other tissues. "The result showed 943 genes including SLC7A2 were enriched in the brown module, which were proved to be associated with proliferation, apoptosis, adhesion and migration of cancer cells by functional enrichment analysis." (PMID 32647070, 2020). "Moreover, lower SLC7A2 has been associated with worse prognosis for some types of cancers and macrophage polarity." (PMID 36639771, 2023). "Like SLC7A1, SLC7A2 is also a cationic amino acid transporter that its function in the regulation of cancer hallmarks is revealed in studies." (PMID 38705513, 2024). "We first analyzed the expression of SLC7A2 in multiple cancers using the TIMER website and confirmed the overexpression of SLC7A2 in normal tissues than HCC tissues." (PMID 34108444, 2021). "qRT-PCR result showed that the expression levels of SLC7A2 were significantly lower in cancer tissues than in normal ovarian tissues." (PMID 32647070, 2020). "But in contrast to SLC7A1, SLC7A2 expression was found to decrease in various cancer types." (PMID 38705513, 2024). "In addition, it was demonstrated that AMPK augments SLC7A2 expression to increase the sensitivity of cancer cells to anti-cancer drugs." (PMID 38705513, 2024). "Moreover, an extensive pan‐cancer analysis was conducted using the TIMER database to assess SLC7A2 levels across 33 prominent human cancers." (PMID 39382373, 2024). "Additionally, given the function of Slc1a3 involved in proliferation in cancer and stem cell have been reported, while Slc7a2 was rarely mentioned." (PMID 38203268, 2023). "Hence, SLC7A2 may offer novel mechanistic insight into the cancer-promoting property of HCC patients." (PMID 36969014, 2023). "We found that the cancer patient treatment-relevant relation between PELO and FOCAD, or the experimentally identified interactions between SLC7A2 and SLC7A1, or SLC7A6 and SLC7A1 were best predicted upon combinatorial normalization (Dataset EV1)." (PMID 40263591, 2025). "The different gene effects of SLC7A1, SLC7A2, and SLC7A3 in pan-cancer highlight their distinct molecular functions in tumors, emphasizing the significance of further exploration." (PMID 41184266, 2025). "The results showed that SLC7A1 displayed significantly lower gene effect score compared to SLC7A2 and SLC7A3, suggesting that SLC7A1 plays a more essential biological role in pan-cancer." (PMID 41184266, 2025). "There were widespread amplifications and deletions of five genes (GPX3, RGS2, MATN3, SLC7A2, and SNCG) across pan-cancer." (PMID 35721114, 2022). "Thus, SLC7A2 may provide new mechanistic insight into the cancer-promoting property of MDSCs." (PMID 34108444, 2021). "Furthermore, we analyzed the functional roles of SLC7A1, SLC7A2, and SLC7A3 in pan-cancer using the CRISPR knockout dataset from the DEPMAP portal." (PMID 41184266, 2025). "Moreover, the expression levels of SLC7A2 exhibit potential as a key prognostic biomarker for HNSCC, offering a new genetic target for the treatment of LNM in this cancer type." (PMID 39382373, 2024). "In addition, MATN3, SLC7A2, and SNCG were significantly upregulated in GC compared with para-carcinoma tissues." (PMID 35721114, 2022).
infection (14 papers, 2013 to 2025). The state of being infected such as from the introduction of a foreign agent such as serum, vaccine, antigenic substance or organism. "Furthermore, loss of colonic goblet cells is another characteristic in mice infected with C. rodentium; when assessed by using periodic acid–Schiff staining, we found that infection resulted in a 47.5 ± 6.5% loss of goblet cells in WT mice compared to only a 25.6 ± 5.3% loss in Slc7a2–/–mice." (PMID 27783672, 2016). "Instead, we showed the miR-372/373/520d family targeting the macrophage’s main arginine transporter SLC7A2/CAT2 during infection." (PMID 38200138, 2024). "On the other hand, the Slc7a1 L-arginine transporter was downregulated during the infection, and Nos2, Arg1, Odc1, and Slc7a2 were expressed at similar levels in uninfected macrophages." (PMID 35202090, 2022). "The expression level of Slc7a2 was significantly increased later (12–24 h) after infection in Ra-infected macrophages compared with macrophages infected with Rv." (PMID 30858471, 2019). "Next, the intracellular survival of Mtb in SLC7A2-overexpressing macrophages was measured 48 h after infection." (PMID 30858471, 2019). "This is in agreement with our observation that the expression levels of both variants of SLC7A2 remain stable in flow cytometry-sorted, GFP-expressing P. berghei-infected Huh7 cells throughout infection." (PMID 28642498, 2017). "We observed that the gene SLC7A2 was induced during infection with EPEC; this expression was completely suppressed in cells transiently transfected with small interfering RNA (siRNA) directed against SLC7A2." (PMID 27783672, 2016). "During the time course of the infection, there was less C. rodentium excreted into the stool by Slc7a2–/–mice in comparison to infected WT animals." (PMID 27783672, 2016). "We studied the role of the L-arginine transporter solute carrier family 7 member 2 (SLC7A2) during infection with the A/E pathogen Citrobacter rodentium." (PMID 27783672, 2016). "SLC7A2 is induced in colonic epithelial cells during the infection and facilitates the intimate attachment of the bacteria, thus initiating the inflammatory response of the infected mucosa." (PMID 27783672, 2016). "Because the difference in colon colonization with C. rodentium between WT and Slc7a2–/–mice occurs as soon as day 1 post-infection, we propose that SLC7A2 plays a crucial role in the early stage of the disease, which is essential for C. rodentium pathogenesis." (PMID 27783672, 2016). "Our work describes a mechanism by which A/E bacteria manipulate host response to favor their colonization, thereby positioning SLC7A2 as an unrecognized therapeutic target to limit infection with enterobacteria." (PMID 27783672, 2016). "Using the murine intestinal pathogen C. rodentium, we showed that SLC7A2 is induced during the infection mainly in CECs and that colonization and inflammation were attenuated in Slc7a2–/–mice, resulting in improved clinical and histological parameters." (PMID 27783672, 2016). "Because Slc7a2 was induced in colonocytes by C. rodentium, we sought to determine the effect of Slc7a2 genetic deletion on the course of the infection." (PMID 27783672, 2016). "Therefore, SLC7A2 plays an important role in some intracellular pathogen infections." (PMID 30858471, 2019). "However, the expression and the role of SLC7A2 in colonic inflammation following infection with intestinal pathogenic bacteria has not been identified." (PMID 27783672, 2016). "However, the infection did not increase or decrease, showing similar behavior to the arginine transporter (Slc7a2)." (PMID 35202090, 2022). "Since we chose miRNAs with the predicted binding site of the 3′UTR of the target genes Nos2, Cat2/Slc7a2, and Cat1/Slc7a1 and because the genes were increased during LPS stimulation but not during infection, it was expected that inhibition would increase the expression of the target mRNAs." (PMID 35202090, 2022).
infection (continued). "By comparison, mRNA expression of the related cationic amino acid transporter genes, SLC7A2 and SLC7A3, did not change after infection, suggesting that these transporters do not play a major role during Toxoplasma infection." (PMID 31194856, 2019).
bacterial infection (2 papers, 2023 to 2025). "In particular, SLC7A2 has been reported to control macrophages’ function toward a bacterial infection and under inflammation in mammal peripheral monocytes." (PMID 37711618, 2023). "Therefore, low expression of slc7a2 in the SL group may have contributed to an inadequate immune response to bacterial infection." (PMID 40356894, 2025).
SLC7A2 also shares sentences with these, for which no sentence is quoted: glioblastoma (2 papers); prostate carcinoma (2); acute myeloid leukemia (1); age (1); bladder cancer (1); diabetes (1); endometrial carcinoma (1); endotoxemia (1); Huntington disease (1); Hyperkalemia (1); ischemia (1); lung fibrosis (1); Lymphatic Metastasis (1); metabolic syndrome (1); neuroblastoma (1); pancreatic ductal adenocarcinoma (1); Salmonella Infections (1).